TLR4 (toll like receptor 4)
Diseases named in the same sentence as TLR4 in open-access papers (continued):
Sharing a sentence is not in itself a finding about the gene and the disease.
eczema (4 papers, 2022 to 2025). "The TLR4 896A > G loci polymorphism is closely associated with disease severity in patients with eczema." (PMID 35907999, 2022). "For instance, drug combinations containing Sophora flavescens–Angelica sinensis inhibit the TLR4/MyD88/NF-κB pathway to treat eczema." (PMID 40612058, 2025). "CTGO significantly improved the skin surface and histopathological characteristics of eczema-affected rats, downregulated the expression of IL-4, TLR4, NF-κB (p65), IL-1β, and TNF-α, and upregulated the expression level of IFN-γ." (PMID 35907999, 2022). "The mechanism of CTGO in treating eczema may be related to regulating related inflammatory factors, promoting the Th1 and Th2 immune balance, and affecting the TLR4/NF-κB signaling pathway." (PMID 35907999, 2022). "We predicted and validated our prediction that CTGO may be used to treat eczema by affecting the TLR4/NF-κB signaling pathway, which provides guidance for future experimental studies." (PMID 35907999, 2022). "Our molecular docking results showed that the overall scores of TNF, TLR4, IL1β, and Alb when docking with four key components were all lower than –5.0 kcal/mol, which suggested that they may play an essential role in CTGO against eczema." (PMID 35907999, 2022).
enteropathy (4 papers, 2018 to 2020). "Therefore, the TLR4/MyD88 axis plays a key role in the development of NSAIDs-induced enteropathy." (PMID 31865463, 2020). "Indomethacin single gavage at 10 mg/kg in TLR-4-mutant mice did not induce small intestinal damages or TNF-α and MCP-1 mRNA expression modulation, suggesting that enteropathy development is independent of LPS/TLR-4/My-D88 pathway activation." (PMID 31527523, 2019).
erectile dysfunction (4 papers, 2022 to 2025). Persistent or recurrent inability to achieve or to maintain an erection during sexual activity. "Erectile dysfunction has been associated with the upregulation of Toll-like receptor 4 (TLR4) expression." (PMID 36568113, 2022).
Fabry disease (4 papers, 2021 to 2025). Fabry disease (FD) is a progressive, inherited, multisystemic lysosomal storage disease characterized by specific neurological, cutaneous, renal, cardiovascular, cochleo-vestibular and cerebrovascular manifestations. "In addition to Fabry Disease, TLR4 has been implicated in other lysosomal storage disorders such as mucopolysaccharidoses and Niemann-Pick Type C." (PMID 38932991, 2024). "The pro-inflammatory feature of Fabry disease also has been well described, with TLR4 pathway-dependent increase in inflammatory cytokines including IL-6, IL-1b, and TNF-a." (PMID 36794069, 2023). "On the other hand, substrate accumulation may also trigger an anomalous activation of other routes, such as the activation of a Toll-like receptor 4 (TLR-4) by Globotrialosil ceramide (Gb3) in Fabry disease (FD), which determines the response of the innate immune system and endothelial disfunction." (PMID 34944420, 2021). "Hence, both in Fabry disease and MPS substrate accumulation is considered to trigger TLR4 and CD1d systems contributing to irreversible organ damage." (PMID 36794069, 2023). "In addition, the interplay of TLR4 signaling and the RAS might contribute to the pathogenesis of cardiovascular changes in Fabry disease." (PMID 40179080, 2025).
femoral head osteonecrosis (4 papers, 2014 to 2025). "Previous study has shown that femoral head osteonecrosis may be caused by disruption of the immune system via lipopolysaccharide- (LPS-) activated toll-like receptor 4 (TLR4) signalling." (PMID 28167850, 2017). "Mongolicin can regulate inflammation and promote bone formation by inhibiting the TLR4/NF-κB pathway and M1 macrophage polarization, reducing the incidence of femoral head osteonecrosis and alleviating pathological manifestations within the femoral head." (PMID 40959091, 2025). "This aligns with findings by S. Okazaki and Shunichiro Okazaki, who underscored the relevance of the TLR4 signalling pathway in the pathogenesis of femoral head osteonecrosis and its augmentation by corticosteroids." (PMID 39069636, 2024). "The objective of the current study was to establish a rat model to investigate the disruption of immune response in steroid-induced femoral head osteonecrosis via Toll-like receptor 4 (TLR4) signaling pathway." (PMID 24428851, 2014). "We have identified that the disorder of immune response via TLR4 signaling pathway plays a role in the pathogenesis of steroid-induced femoral head osteonecrosis." (PMID 24428851, 2014). "Corticosteroids can induce femoral head osteonecrosis by disturbing the immune response via TLR4 signaling pathway." (PMID 24428851, 2014).
Focal cortical dysplasia (4 papers, 2018 to 2024). A type of malformation of cortical development that primarily affects areas of neocortex. "Increased expression of HMGB1 and TLR4 is seen in TLE and focal cortical dysplasia; HMGB1 can enhance both acute and chronic seizure susceptibilities in a TLR4-dependent manner." (PMID 31185666, 2019). "We attempted to determine whether the inflammatory pathway HMGB1-TLR4 and the downstream pro-inflammatory cytokines is upregulated in focal cortical dysplasia (FCD) type II and whether there is a correlation between the TLR4 upregulation and disease duration or frequency of epileptic seizures." (PMID 29382328, 2018).
Fulminant hepatic failure (4 papers, 2019 to 2023). Hepatic failure refers to the inability of the liver to perform its normal synthetic and metabolic functions, which can result in coagulopathy and alteration in the mental status of a previously healthy individual. "It was reported that a substantial decrease in hepatic NF-κB activation has been reported in LPS-induced fulminant hepatic failure TLR4-deficient mice." (PMID 31581526, 2019). "A recent study revealed that CQMUH-011 downregulated the production of multiple pro-inflammatory cytokines by inhibiting the TLR4/NF-κB signaling pathway in an LPS/D-GalN-induced fulminant hepatic failure model." (PMID 33528726, 2021). "Additionally, tectorigenin mitigated experimental fulminant hepatic failure via modulating the toll-like receptor 4 (TLR4)/MAPK and TLR4/NF-κB pathways and autophagy." (PMID 37570873, 2023).
gram-positive bacterial infections (4 papers, 2016 to 2025). Infections caused by bacteria that retain the crystal violet stain (positive) when treated by the gram-staining method. "Thus, it is important to pay attention to the function of TLR4 during Gram-positive bacterial infection." (PMID 33763386, 2021). "However, the role of TLR4 in Gram-positive bacterial infection is less well understood." (PMID 33763386, 2021). "Thus, some Gram-positive bacteria contain TLR4 ligands, and it might be possible that activation of TLR4 at the time of Gram-positive bacterial infection is a common phenomenon." (PMID 33763386, 2021). "However, the role of TLR4 in Gram-positive bacterial infection is less well understood because the bacteria do not contain LPS." (PMID 33763386, 2021). "In addition, we uncovered a remarkable negative impact of the TLR4 pathway in controlling the quality of the inflammatory response and host defense against a gram-positive bacterial infection." (PMID 27550658, 2016). "LPS (activator of TLR4) and LTA (activator of TLR2) were selected to mimic the Gram-negative and Gram-positive bacterial infections, respectively." (PMID 40226627, 2025).
H1N1 influenza (4 papers, 2018 to 2026). "Here, we show that a split H1N1 influenza vaccine (sH1N1) combined with a TLR4 agonist, glucopyranosyl lipid adjuvant formulated in a stable oil-in-water emulsion (GLA-SE), boosts IgG2c:IgG1 ratios, enhances hemagglutination inhibition (HAI) titers, and increases protection in aged mice." (PMID 29515589, 2018).
Hyperammonemia (4 papers, 2021 to 2025). An increased concentration of ammonia in the blood. "We therefore suggest that hyperammonemia leads to liver injury, which is associated with TLR4-mediated liver necroptosis." (PMID 40053595, 2025). "In the present work, TAA induced liver dysfunction and hyperammonemia that associated with enhanced expression of TLR4 brain content as compared to normal rats." (PMID 33855084, 2021). "This neuroprotective impact can be justified by lowering hyperammonemia, improving liver functions, in addition to its antioxidant effect, and suppression of TLR-4/Notch1/NF-κB inflammatory pathway." (PMID 40920270, 2025). "Hyperammonemia induces liver injury, which can be prevented by inhibiting the Toll-like receptor 4 and RIPK1 pathway." (PMID 40053595, 2025). "To validate the finding that TLR4 inhibition protects against hyperammonemia, we studied the effect of the TLR4 antagonist TAK-242 in two clinically relevant animal models of hyperammonemia." (PMID 40053595, 2025). "The Neuro-protective effect of Dapagliflozin was mediated through the reduction of hyperammonemia, the enhancement of hepatic functions, inactivation of TLR4/Notch1/NF-κB pathway, and apoptosis inhibition." (PMID 40920270, 2025). "As TLR4 inhibition in vivo was found to protect against hyperammonemia and hyperammonemia-induced liver injury, these data point toward indirect activation of TLR4 during hyperammonemia, for example, through secreted DAMPs." (PMID 40053595, 2025). "Inhibition of RIPK1 and TLR4 protects against hyperammonemia-induced liver injury and are potential therapeutic targets for hyperammonemia and chronic liver disease progression." (PMID 40053595, 2025). "Inhibition of receptor-interacting serine/threonine-protein kinase 1 (RIPK1) and its upstream inducer Toll-like receptor 4 (TLR4) protected against liver injury and further hyperammonemia." (PMID 40053595, 2025). "This is consistent with previous reports that showed that hyperammonemia following hepatic insult, induces oxidative imbalance along with up-regulation of TLR4 expression." (PMID 40920270, 2025). "The observation that treatment with a TLR4 antagonist reduces circulating ammonia to levels seen with ammonia scavengers in clinically relevant models of hyperammonemia provides the rationale for proof-of-concept clinical studies with TLR4 antagonists." (PMID 40053595, 2025). "Together, oxidative stress and microglia activation induced by hyperammonemia promote upregulation of brain TLR4 and further astrocyte swelling, in a harmony with our results." (PMID 39556255, 2024). "Hyperammonemia induces oxidative stress and releases the pro-inflammatory mediators via activation of toll-like receptor-4 (TLR4)." (PMID 39556255, 2024). "In order to give a better insight, we also examined the role of hyperammonemia, oxidative stress, or inflammation pathways by which D. salina exerts its therapeutic actions in brain via TLR4, HSP-25, and IGF-1 regulation." (PMID 33855084, 2021). "Although we did not explore the role of glutaminase type 1 in the present study, it may partly explain the protective effect of TLR4 in our hyperammonemia models." (PMID 40053595, 2025). "In conclusion, the results of this study provide insights into the deleterious effect of hyperammonemia on progression of liver injury and fibrosis, which is associated with mitochondrial dysfunction and appears to be TLR4 dependent, but the exact mechanism of the interaction is not clear." (PMID 40053595, 2025).
interstitial cystitis (4 papers, 2024 to 2025). A rare chronic debilitating urogenital disease characterized by urinary frequency, urgency, and pelvic pain. "This work was carried out under the project entitled “Mechanisms of exosomes derived from HUC‐MSCs enriched with miR‐9 regulating the activity of NLRP3 inflammasome through TLR4 in the treatment of bladder pain of interstitial cystitis/bladder pain syndrome”." (PMID 38415918, 2024).
interstitial lung disease (4 papers, 2020 to 2024). A diverse group of lung diseases that affect the lung parenchyma. "According to our results, previous studies have shown that the deficiency of TLR4 decreases pulmonary inflammation and fibrosis in the bleomycin-induced lung injury supporting the relationship between TLR4 and interstitial lung disease found in our study." (PMID 32164729, 2020). "Subjects with nailfold capillaroscopy abnormalities had a higher amount of TLR2+ classical and non-classical monocytes and those with interstitial lung disease (ILD) had a higher percentage of TLR4+ non-classical monocytes." (PMID 32164729, 2020).
intracranial aneurysm (4 papers, 2013 to 2022). "Regarding the molecular aspects of macrophage polarization, it has already been shown that toll-like receptor 4 (TLR4) compels macrophages skewedly toward the M1 phenotype in intracranial aneurysms." (PMID 34200256, 2021). "Toll-like receptor 4 (TLR4) is highly expressed in the brain and can be activated by extravasated blood and damaged brain tissues upon the rupture of an intracranial aneurysm." (PMID 35170388, 2022). "In this study, to our knowledge we are the first to demonstrate that T1DM promotes the formation of intracranial aneurysm as well as significantly increases RAGE, MMP9 and TLR4 expression in the intracranial arterial wall compared to WT non-DM rats." (PMID 23844137, 2013). "The increased intracranial aneurysm formation may be regulated by inflammatory factors RAGE, MMP9 and TLR4." (PMID 23844137, 2013).
laryngeal carcinoma (4 papers, 2014 to 2024). Carcinoma that arises from the laryngeal epithelium. "Taken together, KIF26B-AS1 regulates TLR4 expression to augment proliferation and migration of laryngeal cancer cells." (PMID 36224753, 2022). "The results showed that KIF26B antisense RNA 1 (KIF26B-AS1) propels cell proliferation and migration in laryngeal cancer and regulates the toll-like receptor 4 (TLR4) signaling pathway." (PMID 36224753, 2022). "In conclusion, the current study manifested that KIF26B-AS1 regulates TLR4 and activates the TLR4 pathway to promote the malignant progression of laryngeal cancer." (PMID 36224753, 2022). "Suppressor of cytokine signaling 1 (SOCS1), a regulator of cytokine-mediated innate and adaptive immunity, has been reported to inhibit the TLR4–NF-κB pathway in laryngeal carcinoma." (PMID 31318878, 2019). "Furthermore, KIF26B-AS1 plays an oncogenic role in laryngeal cancer via upregulating TLR4 expression as well as the FUS/TLR4 pathway axis, findings which offer novel insight for targeted therapies in the treatment of laryngeal cancer patients." (PMID 36224753, 2022). "We then used the rescue experiments to verify whether KIF26B-AS1 could propel the proliferation and migration of laryngeal carcinoma cells by regulating the expression of TLR4." (PMID 36224753, 2022). "In laryngeal cancer, KIF26B antisense RNA 1 regulates TLR4 and activates the TLR4 signaling pathway to promote malignant progression." (PMID 38463226, 2024).
Liver abscess (4 papers, 2023 to 2025). A circumscribed area of pus or necrotic debris in the liver. "Together, these data suggest that following inoculation, E. coli in the liver signals via TLR4 to promote influx of innate immune cells, which in turn facilitates bacterial replication and development of liver abscesses." (PMID 38096412, 2023). "Therefore, TLR4 signaling mediates a tradeoff between liver abscess development and efficient pathogen elimination." (PMID 38096412, 2023).
Lyme disease (4 papers, 2012 to 2024). Lyme disease (named after the towns in the USA where the disease was first identified) is a bacterial infection caused by Borrelia burgdorferi. "To test if the anti-inflammatory effect of acetate supplementation is specific to a TLR4-mediated injury, we measured markers of neuroglia activation in rats subjected to B. burgdorferi-induced neuroborreliosis that is mediated in large part by a TLR2-type mechanism." (PMID 23134838, 2012).
MALT lymphoma (4 papers, 2014 to 2022). An indolent, extranodal type of non-Hodgkin lymphoma composed of small B-lymphocytes (centrocyte-like cells). "Mucosa associated lymphoid tissue (MALT) lymphoma show strong expression of TLR4 and weak expression of TLR5." (PMID 25112836, 2014). "MALT lymphomas express TLR4 which recognizes LPS derived from Gram-negative bacteria like H. pylori." (PMID 25112836, 2014).
measles (4 papers, 2011 to 2025). A highly contagious viral infection caused by the measles virus. "More recently, the major alleles of coding SNPs in the TLR2 (rs3804100) and TLR4 (rs5030710) genes have been associated with a dose-related increase or decrease in measles-specific antibodies, respectively." (PMID 21933421, 2011). "Moreover, heterozygous variants for two non-synonymous SNPs (Gly299Asp and Ile399Thr) have been identified in the TLR4 gene and associated with higher IL-4 secretion to the measles vaccine strain." (PMID 21933421, 2011).
membranous nephropathy (4 papers, 2014 to 2024). "XIST targets and downregulates mir-217, a negative regulator of TLR4 and downregulation of XIST alleviated podocyte apoptosis and kidney injury in membranous nephropathy by mir-217/TLR4 axis." (PMID 40176927, 2024).
meningococcal meningitis (4 papers, 2016 to 2019). "Our research group previously found that single nucleotide polymorphisms (SNPs) in the Toll-like receptor 4 and 2 genes (TLR4 and TLR2) are highly associated with susceptibility to meningococcal meningitis in children." (PMID 31888554, 2019).
mucopolysaccharidoses (4 papers, 2011 to 2023). "In particular, TLR4 has been shown to be involved in the development of mucopolysaccharidosis (MPS), a heterogenous group of LSD resulting from deficiencies in lysosomal enzymes degrading glycosaminoglycans (GAGs)." (PMID 33057840, 2021). "The TLR4 pathway is also activated in mucopolysaccharidosis (MPS), parallel to the accumulation of glycosaminoglycans (GAGs)." (PMID 36794069, 2023). "There are several findings supporting the hypothesis that inflammation in mucopolysaccharidoses might be triggered through the activation of TLR4 signalling." (PMID 35216110, 2022).
myasthenia gravis (4 papers, 2010 to 2025). Myasthenia gravis (MG) is a rare, clinically heterogeneous, autoimmune disorder of the neuromuscular junction characterized by fatigable weakness of voluntary muscles. "This complements the previously observed aberrant TLR4 signaling in the hyperplastic thymuses of patients with myasthenia gravis." (PMID 34279044, 2021). "Collectively, our results suggest that interferon regulatory factor 1 enhances T cell differentiation by recruiting histone deacetylase 1 to block B cell CD180 transcription in myasthenia gravis via the Toll-like receptor 4/mitogenactivated protein kinases/nuclear factor-kappa B pathway." (PMID 41169211, 2025).
myelofibrosis (4 papers, 2021 to 2025). A partial or complete replacement of the bone marrow stroma by fibrous tissue. "In conclusion, our results suggest that the IGFBP-6/SHH/TLR4 axis is implicated in alterations of the primary myelofibrosis microenvironment and that IGFBP-6 may play a central role in activating SHH pathway during the fibrotic process." (PMID 34905501, 2021). "In primary myelofibrosis, IGFBP-6 has been implicated in the activation of the Sonic Hedgehog (SHH)/Toll-like receptor 4 (TLR4) axis, promoting stromal reprogramming and fibroblast proliferation." (PMID 40723309, 2025). "The present study aims to investigate the involvement of IGFBP-6/sonic hedgehog /Toll-like receptor 4 axis in the microenvironment alterations of primary myelofibrosis." (PMID 34905501, 2021). "Pacritinib is approved for myelofibrosis and inhibits IRAK1 and downstream activation from TLR4, though pediatric studies have not yet been completed." (PMID 37762291, 2023).